BMP4 (bone morphogenetic protein 4)
Diseases named in the same sentence as BMP4 in open-access papers (continued):
Sharing a sentence is not in itself a finding about the gene and the disease.
tumor (continued). "Because, the resultant CAFs with downregulated BMP4 expression provide more conducive environment for deregulated self-renewal of oral-SLCCs, this evolution may be essential for tumor progression." (PMID 30287850, 2018). "Other studies have identified BMP4 as an onco-protein with frequent overexpression in tumor tissues and positive regulation of proliferation, chemo-resistance and metastasis in several cancer cells such as the breast, ovarian, pancreatic, gastric and colon cancers." (PMID 30012194, 2018). "After tumor formation, BMP4 will be upregulated to promote CRC progression and metastasis." (PMID 30158634, 2018). "In addition, an increase in LTC-IC after exposure to BMP4 confirmed the involvement of this cytokine provided by the tumor niche and of its receptor in promoting AML stem-like cells." (PMID 30262802, 2018). "Immunohistochemical analysis verified specific BMP4 expression in metastatic tumor cells, which could be blocked by antibody incubation with an excess of BMP4 control peptide." (PMID 29670000, 2018). "Moreover, receiving Rapa treatment facilitated HCCLM3 cells growth and the difference of average tumor weight and average tumor volume in si-BMP4 + Rapa group was statistically significant higher than si-BMP4 group (p < 0.001, respectively)." (PMID 30012194, 2018). "Indeed, BMP4 involvement in resistance to treatment has been demonstrated in several tumor types, including HCC50 and ovarian cancer." (PMID 30262802, 2018). "The effects of modulation of these signaling pathways on the differentiation and tumor potential via enhancing the activity of Activin A and BMP4 signaling pathways and inhibiting of MEK/ERK and PI3K/Act signaling pathways in RA-stimulated ES R1 cells were studied in the next series of experiments." (PMID 28798778, 2017). "Additionally, in a mouse model, BMP-4 suppressed metastasis, seemingly by regulating anti-tumor immune responses." (PMID 28733469, 2017). "We demonstrate that tumor-derived HH drives CA-MSC BMP4 production." (PMID 26755648, 2016). "Furthermore, different BMP ligands such as BMP2, BMP4, BMP6 and BMP7 induce angiogenesis, and BMP2 and BMP4 promote tumor angiogenesis." (PMID 27977771, 2016). "However, the functional effects of active BMP4 signaling have been investigated in vitro in various cancer cell lines, showing the possibility of a tumor-specific reaction upon BMP4 activation." (PMID 27191723, 2016). "BMP-4 is a member of the BMP family that stimulates tissue formation and differentiation, and the abnormal expression of BMP-4 may be associated with tumor development." (PMID 26506239, 2016). "In colorectal cancer and nervous system tumors, BMP-4 promotes the differentiation, apoptosis, and chemo-sensitization of CSCs and restricts the self-renewal capacity of CSCs, which plays an inhibitory role on tumor progression." (PMID 27661009, 2016). "BMP4 in turn increases tumor HH expression, thus creating a positive feedback loop." (PMID 26755648, 2016). "Given the HH-mediated induction of BMP4 in CA-MSCs, we investigated if tumor derived HH could likewise induce BMP4 expression." (PMID 26755648, 2016). "We therefore hypothesized that CA-MSC-derived BMP4 may alter HH expression in tumor cells though a feedback mechanism." (PMID 26755648, 2016). "Additionally, BMP-4 reduces the secretion of G-CSF and decreases the number and activities of MDSCs by counteracting NF-κB activity in tumor cells." (PMID 27661009, 2016). "Univariate analysis showed that low BMP4 levels were correlated with high tumor grade." (PMID 26487967, 2015). "Because elevated level of MMP-9 is well known to increase the migratory properties of tumor cells in vivo and in vitro, we next tested whether BMP-4 was able to suppress the invasion of HT1080 cells." (PMID 25897433, 2015). "Neutralization of BMP2 and BMP4 in mice inhibited xenografted tumor growth induced by Dragon." (PMID 26029998, 2015).
tumor (continued). "Bone morphogenetic protein 4 (BMP4) is another tumour migration and invasion regulator." (PMID 25598425, 2015). "BMP2 and BMP4 are less expressed in tumor cells, osteoblast-like cells and stromal cells." (PMID 25529855, 2014). "The BMP-4 expression levels in biopsy tumor samples were determined by immunohistological staining." (PMID 24779016, 2014). "Collectively, these studies suggest that BMP4 expressed in tumor tissues may act as a novel marker for predicting the prognosis of cancer patients, including patients with NSCLC." (PMID 24779016, 2014). "We briefly stimulated fibroblasts with BMP4 and then added tumor cells to Matrigel covered invasion chambers and found that fibroblasts could not only increase invasion through the matrix, but be inhibited pharmacologically with DMH1." (PMID 23840733, 2013). "Meantime, the expression level of BMP4 are frequently altered in many tumor types." (PMID 23590708, 2013). "At a higher tumor burden, the BMP-4 virus delayed tumor growth compared to the parental virus." (PMID 23800258, 2013). "BMP4 may also play different roles during different tumor stages, but its mechanism in both benign and malignant tumors of the nervous system requires further study." (PMID 24099560, 2013). "Moreover, BMP4 protein expression in tumor tissues was significantly lower than that inparacancer tissues (P = 0.001)." (PMID 24099560, 2013). "Importantly, mating these mice with BMP4 transgenic mice under the same promoter rescued the tumor phenotype indicating that inhibition of BMP signaling mediated the effects of the noggin transgene." (PMID 22168923, 2011). "In addition, BMP4 promotes glial differentiation of progenitor cells from the forebrain subventricular zone and CNS derived tumor cells." (PMID 21687800, 2011). "The treatment of CD133+ CR-CSCs with BMP4 induces in vitro differentiation and reduces their tumorigenic potential; moreover in vivo the combined treatment with BMP4 and conventional chemotherapeutics reduces the tumor size." (PMID 24212789, 2011). "The rationale of this experiment is that if the tumor phenotype is caused by specifically inhibiting BMP signaling, overexpression of BMP4 under the same promoter could at least partially block the inhibition." (PMID 22168923, 2011). "For example, BMP-2 and -4 inhibit prostate cancer cell growththrough Smad-1 phosphorylation, p21WAF1/ cip1 up-regulation, and Rbdephosphorylation, while in glioblastoma, BMP4 and its cognate receptors cantrigger the Smad signaling cascade to reduce the proliferation of tumor cells." (PMID 20157553, 2009). "Among the nine cell states associated with fibroblasts, five (ADAMDEC1+ fibroblast, BMP4+ fibroblast, intestinal smooth muscle, myofibroblast, PI16+ fibroblast) were identified as NAT-enriched, and three (WNT5A+ fibroblast, pericyte, desmoplastic fibroblast) were identified as tumor-enriched." (PMID 40032993, 2025). "BMP4 treatment could potentially limit GBM progression by promoting tumor cell differentiation." (PMID 39063221, 2024). "Additionally, tumor cells expressed Bmp2 and low levels of Gdf11, Bmp4, and Tgfb1." (PMID 38304252, 2023). "The ablation of IPO5 using siRNA reduced BMP4-induced SNAI2 expression in TCam-2 cells, revealing a link between IPO5 levels and BMP4 signalling outcomes that may regulate the levels of an important transcription factor of known general importance to tumour metastasis." (PMID 37048077, 2023). "High-risk prognostic genes BMP4, CELSR3, GPRC5C, and RUNDC3B, highly expressed in Epithelial Cells, CCBE1 showed expression in Leydig cells, SCGB2A2 highly expressed in Epithelial Cells and Cancer cells, suggesting that Epithelial cell play an important role in tumor growth and initiation." (PMID 37985782, 2023). "BMP4 could serve as a tumor suppressor in LUSC and inhibited the growth of LUSC cells." (PMID 35021154, 2022).
tumor (continued). "Furthermore, BMP4 was capable of inducing tumor dormancy via activating SMAD1/5 signaling and BMP7 can inhibit tumor cell growth and drive CSCs into dormancy by mediating the expression of N-myc downstream-regulated gene 1 and activating p38 MAPK and p21 signaling pathways." (PMID 34712663, 2021). "In addition, BMP4 down-regulation in the tumor micro-environment could lead to the formation of these clusters and thus increase tumor cell metastatic ability." (PMID 32093026, 2020). "Previous reports imply that several transcription factors, such as SMAD3/5, can bind to the promoter region of CD73;16 therefore, we hypothesised that TGF-β1 or BMP4, both of which are highly expressed in the tumour microenvironment, may function as a catalyst in this interaction." (PMID 32345959, 2020). "Consequently, BMP4 and its related molecular pathways may be worthy of further investigation and help lay the foundation for better anti-tumor therapies." (PMID 32201526, 2020). "Moreover, BMP4 was significantly upregulated in tumor in GSE13861." (PMID 30134903, 2018). "Therefore, the upregulation of BMP4 in this case with several tumour relapses might be supportive of its role as a marker for bad prognosis." (PMID 26998479, 2015). "BMP4 induction of IL-6 could enhance the inflammatory tumor microenvironment." (PMID 23840733, 2013). "An interesting antitumorigenic activity has been demonstrated for BMP4 protein, since it reduces VEGF expression, thereby inhibiting angiogenesis within the tumor microenvironment and consequently suppressing tumor growth." (PMID 41596411, 2026). "As a member of TGF-β superfamily, BMP4 promotes epithelial-mesenchymal transition (EMT) via the canonical Smad signaling pathway, thereby driving tumor cell metastasis and invasion." (PMID 40140925, 2025). "The main mechanisms by which GLP—1RAs promote tumor apoptosis encompass the cAMP—PKA—dependent pathway, the BMP4/Smad signaling pathway, the PI3K/Akt/mTOR signaling pathway, and the NF-κB signaling pathway." (PMID 40140925, 2025). "BMP4 has been shown to drive differentiation of GSCs towards a predominantly glial (astrocytic) fate, to reduce GBM tumor burden in vivo and to improve survival in a mouse model of GBM." (PMID 41279885, 2025). "This intricate signaling axis of WNT, BMP4, and NOTCH roads suggests a multifaceted regulatory structure in NB, where its interactions significantly influence tumor differentiation and growth suppression." (PMID 40429864, 2025). "BMP2, BMP4, and BMP7 are canonical growth-inhibitory ligands known to suppress tumor progression by inducing apoptosis and inhibiting EMT in CRC and other cancers." (PMID 40564222, 2025). "To assess the potential of BMP4 as a differentiation therapy, we develop a mathematical model that describes the growth of a GBM tumor via a hierarchy of GSCs, progenitor cells and terminally differentiated cells." (PMID 41279885, 2025). "BMP4 was slightly upregulated in stage IVA patients, while the EP300 gene was remarkably upregulated as the tumor stage advanced, especially in stage III patients." (PMID 38539520, 2024). "Since BMP4 is a secreted protein, we conclude that it can act both in an autocrine manner in SMAD4-expressing tumor cells and in a paracrine manner on stromal cells to suppress metastasis." (PMID 38689334, 2024). "Upon tumor confirmation at day seven, the tumor was resected and a total of 0.25×106 MSC1 transfected with NPs containing mCherry or BMP4 were encapsulated in a 10 μL microbubble of TISSEEL and implanted in resection cavity." (PMID 39545093, 2024). "Accordingly, it was shown that BMP4 treatment promotes the differentiation of DIPG tumor cells, in line with its putative tumor suppressor activity." (PMID 39373720, 2024). "Then, the BMP4-producing vaccinia viruses were delivered intracranially in an orthotopic mouse model of GBM, and resulted in tumor regression and better mice survival." (PMID 38256140, 2024).
tumor (continued). "To avoid paracrine signalling by BMP4, we enforced the expression of a constitutively active BMP receptor, caBMPR1a, in the 231-HM tumor cells." (PMID 38689334, 2024). "Using the clinical HCC samples, we confirmed that both BMP4 expression and glycogen content significantly increased in HCC tissues, compared with that in adjacent non-tumor tissues by IHC and PAS staining assays." (PMID 37443106, 2023). "BMP4, GDF15 and ACVR1B were positively correlated with both ER and HER2 in Luminal B (ER+, HER2+) tumours." (PMID 37333824, 2023). "While the reduction of the BMP-Smad1/5/8 axis is in line with increased levels of Erfe, we do not observe a decreased expression of BMP ligands, such as BMP2, BMP4, and BMP6, in the skeletal muscle of C26 tumor-bearing mice." (PMID 38052214, 2023). "To determine the molecular basis of the anti-tumor activity of FSTL1 in CC, we first examined the Smad-mediated BMP4 signaling." (PMID 36756161, 2023). "In a patient-derived xenograft model, IRDye800cw-labelled C4C4 and C8C8 effectively target BMP4 and BMP2/4, respectively, and inhibit tumor growth." (PMID 37746282, 2023). "BMP4, GDF15 and ACVR1B were expressed at higher levels in HER2 positive tumours which were correlated with poorer OS." (PMID 37333824, 2023). "To analyse the expression of proteins of interest in the PDX model, we performed IHC staining for BMP2, BMP4, SMAD4 and SHH on tumor, lung and colon tissue 28 days post treatment." (PMID 35902550, 2022). "BMP4 and EPCAM are involved in inducing epithelial-mesenchymal transition (EMT) and promoting tumor cell migration of ESCA." (PMID 35069736, 2022). "In turn, the induction of the pluripotency genetic network also induces BMP4 signaling and generates a regulatory feedback loop that maintains the CSC pool within the tumor." (PMID 35565225, 2022). "Notably, BMP4 may have diverse effects depending on the tumor type." (PMID 34249928, 2021). "The difference in expression comparing tumor and normal tissues were found to be significant in eight genes (PLAU, EGR1, IL6, EGFR, EZH2, BMP4, CCNB1, NMI)." (PMID 34077304, 2021). "Consistently, IHC staining of xenograft tumor tissues using TGF-β, BMP4, ICAM1 and VCAM1 antibodies indicated suppression of the TGF-β signaling pathway status in PGAM1 silencing cancer cells compared to that in the control group." (PMID 32855383, 2020). "Treatment with exogenous BMP4 also decreases GSC tumorigenicity in vivo and reduces tumor cell proliferation." (PMID 32102285, 2020). "We observed that bone morphogenetic protein 4 (BMP4) delivery and thymosine β4 targeting display anti-tumor activity in colorectal (CR) cancer by inducing CR-CSC differentiation and inhibition of PI3K/AKT pathway through the contribution of PTEN upregulation." (PMID 31366089, 2019). "The list of top upregulated genes in R1 cell-derived tumor xenograft versus parental cell-derived tumor xenograft also included ID1 and BMP4." (PMID 31013771, 2019). "Together with the tumor stem cell markers, CD44 and CD133, AC were found also to express the paracrine factors, BMP4, FGF, and SHH." (PMID 31191748, 2019). "BMP4, a member of TGF-β family and a direct target of Wnt signaling in CRC, is first identified as a tumor suppressor in the initiation of various cancers including CRC22,32,33." (PMID 30158634, 2018). "Supporting the notion that these modules represent specific signatures, genes known to be expressed in tumour epithelium, such as WNT targets (e.g. AXIN2, NOTUM), FGF3 and BMP4 were contained in the brown module [Suppl." (PMID 29541918, 2018). "In the present study, three BMPs members belonging to the Transforming growth factor beta (TGF-β) superfamily, namely BMP3, BMP4 and BMP7, were found hyper-methylated in cDLBCL, supporting the role of BMP families as tumor suppressor genes." (PMID 28912427, 2017).
tumor (continued). "Treatment of dental epithelial cell line, mDEC6 with bone morphogenetic protein 4 (BMP4), a known tumor inhibitor, leads to translocation of FRG1 from the nucleus to the cytoplasm." (PMID 28947680, 2017). "All together, our data imply that BMP4/Smad1 signaling can be inhibited through SMAD1 repression by miR-26b-5p, thus suppressing EMT, tumor invasion and metastasis." (PMID 27027434, 2016). "The reciprocal induction of tumor derived HH by BMP4 creates a possible signaling loop with tumor derived HH and CA-MSC derived BMP4." (PMID 26755648, 2016). "Interruption of this loop with a HH pathway inhibitor or BMP4 blocking antibody decreases CA-MSC-derived BMP4 and tumor-derived HH preventing enrichment of CSCs and reversing chemotherapy resistance." (PMID 26755648, 2016). "Supporting a positive feedback loop between tumor derived HH and CA-MSC derived BMP4, there was a 3-fold reduction in BMP4 protein levels in SKOV3+CA-MSC tumors treated with IPI-926 compared to SKOV3+CA-MSC untreated tumors." (PMID 26755648, 2016). "Over-expression of miR-26b-5p inactivated the bone morphogenetic protein 4 (BMP4)/Smad1 pathway by upregulating SMAD1 in HCC cells and suppressing EMT, tumor migration and invasion." (PMID 27027434, 2016). "When compared to the normal human astrocytes (NHAs) and hNSCs, hNSCs-BMP4 could significantly inhibit the invasive growth of hGSCs, promote their differentiation and apoptosis by activating Smad1/5/8 signaling, and prolong the survival time of the tumor-bearing nude mice." (PMID 26908439, 2016). "Further highlighting the complexity of HH signaling, we demonstrate that both tumor derived SHH and IHH form a signaling loop with CA-MSC-derived BMP4." (PMID 26755648, 2016). "Based on the staining intensity, BMP-4 and CDH1 demonstrated a higher protein expression and/or increased positivity in lung metastases when compared with the primary tumor tissues." (PMID 26059540, 2015). "Liposomal clodronate treatment impairs BMP4 induction, delays development of stress BFU-E of spleen and severely reduces peripheral erythroid in tumor-bearing mice, consistent with the requirement of macrophages to mount BMP4-mediated stress erythropoiesis." (PMID 25822717, 2015). "These immunohistochemical data suggest that tumor cells expressing BMP5 and BMP6 induce the transformation of mesenchymal cells, which normally express BMP2 and BMP4, in preosteoblasts and osteoblasts." (PMID 25529855, 2014). "Five hypermethylated loci harbored by four genes (GSTP1, TACSTD2, BMP4 and RASSF1) and three hypomethylated loci in three genes (ARHGAP8, GPR35 and DLGAP1) were validated using 7 assays with 12 tumor-normal tissue pairs from this study." (PMID 23437062, 2013). "The tumor formed by CMT U309, clone 6, i.e. a clone highly expressing BMP-4 in vitro, was strongly positive for BMP-2/4." (PMID 19771160, 2009). "A study realised on cerebellar primitive neurectodermal tumor cell line demonstrated that a high concentration of BMP2 and BMP4 attenuate apoptosis." (PMID 15369599, 2004). "CAFs, one of the most prevalent cell types in the tumor microenvironment of PDAC, could upregulate the expression of TFAP2A through BMP4." (PMID 40727938, 2025). "Neither TGF-B1, BMP4 and GREM1 transcript levels nor ID1 and pSMAD2 protein expression were significantly associated with survival in either tumour or stromal compartments." (PMID 40826447, 2025). "All mathematical models rely on simplifying assumptions, and ours is no exception; we do not claim to capture the full complexity of a GBM tumor or its response to BMP4-AMSC therapy, which itself is not yet fully understood." (PMID 41279885, 2025). "In the presence of SMAD4, enforced expression of BMP4 did not change the rate of tumor growth up to the day of resection." (PMID 38689334, 2024).